OR4Q2 (olfactory receptor family 4 subfamily Q member 2 (gene/pseudogene))
Description:
Odorant receptor.
Synonyms: formerly OR4Q2P
Gene: Protein-coding gene on chromosome 14 (19,999,913 to 20,004,760, forward strand). Ensembl gene ENSG00000196383.
Subcellular location: Cell membrane
Pathways (Reactome):
Sensory Perception: Expression and translocation of olfactory receptors
Homologues: Orthologues: macaque OR4Q2 (61% identical), dog OR4Q2 (58% identical), rabbit OR4Q2 (54% identical). Paralogues in human: OR4M1 (39% identical), OR4M2B (38% identical), OR4M2 (38% identical), OR4N5 (37% identical), OR4Q3 (37% identical), OR4N2 (37% identical), OR4D1 (36% identical), OR4C12 (35% identical), OR4C15 (35% identical), OR4K14 (35% identical), OR4N4 (35% identical), OR4N4C (35% identical), and 116 more.